KLK10 (kallikrein related peptidase 10)
Diseases named in the same sentence as KLK10 in open-access papers (continued):
Sharing a sentence is not in itself a finding about the gene and the disease.
tumor (continued). "Like in immunohistochemistry of native tumour, KLK6 expression in cell lines was more distinct than that of KLK10." (PMID 18854834, 2008). "KLK10 and KLK6 are members of the kallikrein family of 15 known proteases in humans, which play an emerging role in tumour microenvironment, invasion and angiogenesis." (PMID 18854834, 2008). "The analysis of the kallikrein-related peptidase family in CRC tumor samples from The Cancer Genome Atlas (TCGA) database identified a distinct pattern of overexpression of KLK6 along with elevated expression of KLK7, KLK8, and KLK10." (PMID 39594797, 2024). "KLK10 exon 3 hypermethylation correlated to tumor-specific lack of KLK10 expression in cancer cell lines and primary tumors." (PMID 29690914, 2018). "Similarly, mice xenografted with cells overexpressing KLK10, 5/6, 5/10, 6/10 had a significant survival advantage over their respective control mice, while mice with KLK6-secreting tumours had significantly decreased survival." (PMID 22102857, 2011). "A pilot study was first conducted to ensure the recombinant KLK10 had no side effects in healthy mice before testing it in tumour-bearing animals." (PMID 22102857, 2011). "Our results suggest that over-expression of KLK10-targeting miRNAs can lead to KLK10 protein down-regulation with subsequent negative effect on tumour cell proliferation." (PMID 20354523, 2010). "KLK10 showed no expression in eight tumours, lower than normal in five and compared to normal in one tumour." (PMID 14710225, 2004). "Functional enrichment analysis showed that higher KLK10 expression was involved in tumor cells adhesion, invasion, metastasis, and immune cell infiltration, which highlighted the potential mining value of KLK10 in CRC progression and the tumor immune microenvironment." (PMID 37938164, 2023). "Moreover, high KLK10 expression was markedly related to poor RFS based on the median of the KLK10 expression levels, highlighting its potential function as the tumor promotor in the occurrence and development of CRC." (PMID 37938164, 2023). "While we do not know whether the cells failed to implant in the presence of KLK10 at the time of injection, or the tumours regressed later during the treatment, the substrate-dependent growth of the clones suggest the former." (PMID 22102857, 2011). "It is unclear how KLK10 may mediate its anti-tumour effects, however the absence of toxicity in mice and the potent in-vitro response to the recombinant KLK10 peptide suggest a promising therapeutic window." (PMID 22102857, 2011). "Results showed that IFI27, KIF20A, KLK10 and TOP2A were significantly upregulated in tumor cells relative to normal cells, whereas SPINK7 showed no differential expression." (PMID 41008826, 2025). "The mean percent tumor core stained for KLK1, KLK7, KLK9 or KLK10 across grades III and IV were not significantly different." (PMID 26231762, 2015). "However, the limited expression of both KLK10 and KLK11 in healthy tissue, together with the overall negative impact on tumor progression make both KLKs interesting therapeutic targets, in addition to their biomarker potential." (PMID 36294951, 2022).
cancer (45 papers, 2002 to 2026). A tumor composed of atypical neoplastic, often pleomorphic cells that invade other tissues. "Despite Klk10 being identified years ago as being prominently associated with cancer regulation, little is known about its biological involvement in intestinal diseases." (PMID 26151867, 2015). "Importantly, KLK9 participates in protease networks within the KLK family and has been implicated in the activation of KLK10, thereby linking its activity to broader biological processes that extend into immunity and cancer biology." (PMID 41516101, 2025). "KLK10 has been involved in the development of many cancers, such as ovarian, breast, prostate and thyroid cancers, although the specific role of KLK10 in tumorigenesis is not yet sufficiently defined." (PMID 37033229, 2023). "In humans, normal plasma KLK10 levels are ~0.5 ng/ml, with a range from nearly undetectable to ~20 ng/ml in various cancers patients." (PMID 35014606, 2022). "Three of these proteins—CCL15, CHGA, and KLK10— are known to be prognostic markers for various types of cancer, and upregulation of these proteins is correlated with poorer prognosis." (PMID 36613555, 2022). "Kallikrein-related peptidase 10 (KLK10) was identified in 1996 as normal epithelial cell-specific 1, involved in cancer development by regulation of cell growth, invasion, and apoptosis." (PMID 34638601, 2021). "On the one hand, different from those in the HD-MSCs group, AA-MSCs highly expressed proinflammatory and cancer-associated genes (IL1B, IL-24, CXCLs, FOS, KLK10)." (PMID 32054519, 2020). "In urine DNA, some markers like HOXD3, HOXA7, GPR62 and KLK10 were detected with comparable frequency from all cancer patients and are candidates for biomarker panels used for the early detection of PCA." (PMID 31297302, 2019). "Most of these studies showed high expression of KLK10 in cancer lesions, although one study reported downregulation of KLK10 mRNA expression in GC tissues." (PMID 28418926, 2017). "Cytoband location 19q13.3–q13.4 was common for differentially expressed KLK gene family (KLK12, KLK11, KLK10, and KLK13), the serine proteases encoded from this Kallikrein gene family have been implicated in various cancers." (PMID 25505737, 2014). "This is in agreement with our unpublished data showing overexpression of several kallikreins (KLK6, KLK7, KLK10) on the mRNA level of cancer samples as compared with their paired normal colon mucosa." (PMID 19367279, 2009). "Moderate KLK10 expression levels (average 85 tpm) were detected in four out of eight normal breast tissues, but expression was undetectable in all cancer libraries tested." (PMID 14710225, 2004). "More research into the KLK10 gene’s molecular basis could contribute to a new therapeutic target for this frequent cancer." (PMID 35669967, 2022). "Methylation of KLK10 would be a novel prognostic marker of cancers." (PMID 25903558, 2015). "In vitro results suggest KLK10 may be cytotoxic to cancer cells at high concentrations and that a component of fetal calf serum can inhibit this toxicity." (PMID 22102857, 2011). "However, contradictory results have been reported in other studies, claiming that KLK10 is upregulated in cancers, as breast, ovarian, gastric and head and neck." (PMID 19367279, 2009). "Kallikrein-10 (KLK-10) is a serine protease that is aberrantly expressed in HNSCC and plays a vital role in the cancer onset and progression." (PMID 37686036, 2023). "The pathophysiological mechanisms driving the tumorigenic properties of KLK10 and KLK11 have been addressed in several studies on various cancer types." (PMID 36294951, 2022). "At stage 3, STARD13, CBFA2T3, RECK, and SASH1 had strong accordant/discordant effects on expression of genes in cancer, while APC, EXT1, NBL, KLK10, and PTCH1 had very weak accordant/discordant impacts on expression of genes in cancer." (PMID 33580150, 2021).
cancer (continued). "Using the KLK-CANMAP, a tool that includes several other cancer datasets, we again found the KLK6, KLK7, KLK8 and KLK10 cluster, with the exception of KLK11, which was upregulated in PDAC compared to normal pancreas tissues." (PMID 34439122, 2021). "These implicate that S-scores and N-scores can allow one to find another type of biomarkers such as EXT1, PTCH1, KLK10, APC, TRIM13 that have strong information sensitive to early cancer." (PMID 33580150, 2021). "Accumulating evidence indicates that microRNAs (miRNAs) are involved in post-transcriptional regulation of several KLK genes in cancer, e.g. KLK6 and KLK10." (PMID 32028882, 2020). "This value is comparable to that of serum CEA (0.86) or KLK10 mRNA (0.89) and higher than that of CA19-9 (0.58), suggesting that Ct-OATP1B3 mRNA may possess the clinically useful level of diagnostic power necessary to discriminate between cancer and normal colon tissues." (PMID 25625007, 2014). "Both KLK7 and KLK10 expressions were significantly higher in the cancer group than those of the non-cancer group (P < 0.05)." (PMID 37868053, 2023). "With respect to the genes having interaction(s) with miRNAs, we realized four down-regulated vDEGs (TMEM100, MYH11, CHRDL1, and FAM107A) to the accompaniment of five up-regulated vDEGs (KLK10, CLDN1, SLC6A6, MMP11, and SLC7A5) being documented by the GEPIA in both COAD and READ cancer types." (PMID 35333898, 2022). "In addition, numerous studies have been conducted to identify new clinically useful cancer biomarkers, as exemplified by Kallikrein-related peptidase 10 (KLK10) mRNA, which shows a cancer-specific profile." (PMID 25625007, 2014). "Indeed, except for that PTCH1, KLK10, TBRG1, NBL1 and EXT1 did not act on gene expression in stage-2 cancer, the other 21 TS gene had larger positive network effects on gene expression than negative network effects in cancer." (PMID 33580150, 2021).
adenocarcinoma (1 paper, 2004). A common cancer characterized by the presence of malignant glandular cells. "Kallikreins are being investigated as potential serum markers for adenocarcinomas such as prostate (KLK2), breast (KLK10, 12, 13) and ovary (KLK6, 8, 10, 11)." (PMID 14760385, 2004).
infection (1 paper, 2015). The state of being infected such as from the introduction of a foreign agent such as serum, vaccine, antigenic substance or organism. "Lower transcription levels of NUDT14, KLK10, SLC28A1, SMAD4 and SEPT7 during a series of stages of infection may reflect the inabilities of these genes to participate in glucose metabolism, tumorigenesis, nucleoside biosynthesis and transport, signaling and microtubule stabilization respectively." (PMID 25903558, 2015).
KLK10 also shares sentences with these, for which no sentence is quoted: acute lymphoblastic leukemia (4 papers); breast tumor (3); hepatocellular carcinoma (2); lymph node metastasis (2); non-small cell lung carcinoma (2); pancreatic adenocarcinoma (2); testicular cancer (2); adenoma (1); amyloid (1); aneurysm (1); carcinomas of the skin (1); cardiovascular disease (1); cerebral aneurysms (1); chromophobe renal cell carcinoma (1); chronic obstructive pulmonary disease (1); clear cell carcinoma (1); endometrial carcinoma (1); esophageal cancer (1); germ-cell tumours (1); HCMV infection (1); Hepatitis C virus (1); hepatoblastoma (1); hereditary colorectal cancers (1); infertile (1); influenza (1); intestinal diseases (1); Lynch syndrome (1); Obesity (1); papillary renal cell carcinoma (1); psoriasis (1).
A further 7 diseases each share a sentence with KLK10 in 1 paper.